ZFP91 (ZFP91 zinc finger protein, atypical E3 ubiquitin ligase)
Diseases named in the same sentence as ZFP91 in open-access papers (continued):
Sharing a sentence is not in itself a finding about the gene and the disease.
pancreatic cancer (6 papers, 2020 to 2024). "In our study, we analysed TCGA and GEO data sets and found that high expression of ZFP91 in pancreatic cancer is associated with worse survival." (PMID 33755268, 2021). "Among the gene sets which were associated with ZFP91 level, cancer invasiveness, pancreatic cancer, TGF‐β signalling and β‐catenin related gene sets were found significant." (PMID 33755268, 2021). "This study aimed to elucidate the exact role of ZFP91 in tumour progression of pancreatic cancer and underlying mechanisms." (PMID 33755268, 2021). "ZFP91 overexpression is prevalent in pancreatic cancer and negatively correlates with overall survival." (PMID 38957318, 2024). "The results showed that GRg3 was able to reduce the expression of ZFP91 in pancreatic cancer cells in a dose-dependent manner, improve ZFP91-induced tumor resistance and enhance the drug sensitivity and antitumor efficacy of GEM." (PMID 38957318, 2024). "And it has been displayed that ZFP91 promotes pancreatic cancer propagation, move, and invasion by the activation of β-catenin signaling." (PMID 35165513, 2022). "ZFP91 promoted proliferation, migration and invasion in pancreatic cancer through the activation of β‐catenin signalling pathway, which was conductive to tumour progression." (PMID 33755268, 2021). "Without significantly difference in mouse weight, the results revealed that the sensitivity of pancreatic cancer to chemotherapies was enhanced by the disruption of ZFP91." (PMID 33755268, 2021). "The gene set enrichment analysis (GSEA) revealed that several TGF‐β, invasiveness and β‐catenin‐related gene sets were enriched in ZFP91 high‐expressed pancreatic cancer patients." (PMID 33755268, 2021). "We analysed the correlation between ZFP91 expression and pancreatic cancer through TCGA and GEO data sets." (PMID 33755268, 2021). "In our study, we demonstrated that the mRNA expression of ZFP91 gene was significantly upregulated in pancreatic cancer compared with normal pancreas tissues according to Gene Expression Omnibus (GEO)." (PMID 33755268, 2021). "We demonstrated that ZFP91 promoted pancreatic cancer proliferation, migration and invasion through activating β‐catenin signalling." (PMID 33755268, 2021). "Then, we found that ZFP91 KD inhibited the proliferation, migration and invasion of pancreatic cancer cells." (PMID 33755268, 2021). "According to growth curve analysis, ZFP91 KD impaired proliferation ability in pancreatic cancer cells." (PMID 33755268, 2021). "Previous studies have demonstrated that ZFP91 is a tumour promotor in several cancers and elevated in pancreatic cancer." (PMID 33755268, 2021). "ZFP91 overexpression is prevalent in pancreatic cancer and negatively correlated with overall survival." (PMID 33755268, 2021). "High expression of ZFP91 gene negatively correlated with overall survival in patients with pancreatic cancer." (PMID 33755268, 2021). "KP4 and HuP‐T3 has relatively high expression of ZFP91 compared with other pancreatic cancer cell lines." (PMID 33755268, 2021). "Taken together, our study clearly demonstrated that ZFP91 promoted pancreatic cancer proliferation, migration and invasion, which was mediated by β‐catenin signalling." (PMID 33755268, 2021). "LINC00491 aggravated pancreatic cancer progression by microRNA 188-5p (miR-188-5p)/Zinc finger protein 91 (ZFP91) axis, which may open up new avenues for the development of prevention and treatment of PC in the future." (PMID 35399733, 2022). "Our study revealed a new mechanism that ZFP91 promoted pancreatic cancer cell proliferation, migration and invasion through activating β‐catenin pathway, implying that ZFP91 might be a potential therapeutic target for pancreatic cancer." (PMID 33755268, 2021). "Since EMT was associated with all the three gene sets, we hypothesized that ZFP91 promoted EMT in pancreatic cancer by activating β‐catenin, which was confirmed by western blot analysis." (PMID 33755268, 2021).
pancreatic cancer (continued). "ZFP91 knock‐down attenuated proliferation, migration and invasion of pancreatic cancer cells." (PMID 33755268, 2021). "ZFP91 knockdown (KD) suppressed pancreatic cancer cell proliferation in KP4 and HuP‐T3 cell lines." (PMID 33755268, 2021). "In addition, higher ZFP91 mRNA and protein expression was detected in pancreatic tumour tissues compared with normal adjacent tissues." (PMID 33755268, 2021). "ZFP91 might be a potential therapeutic target for pancreatic cancer." (PMID 33755268, 2021). "However, the exact role of ZFP91 in pancreatic cancer progression and related signal transduction mechanism remains unclear." (PMID 33755268, 2021). "ZFP91 might be a promising therapeutic target of pancreatic cancer." (PMID 33755268, 2021). "In transwell invasion assay, ZFP91 KD KP4 cells also exhibited impaired invasion ability, revealing that ZFP91 was involved in migration and invasion of pancreatic cancer cells." (PMID 33755268, 2021). "ZFP91 also facilitated EMT and chemoresistance in pancreatic cancer." (PMID 33755268, 2021). "ZFP91 promoted EMT and chemoresistance in pancreatic cancer." (PMID 33755268, 2021).
acute myelogenous leukemia (4 papers, 2014 to 2022). "Unoki and his colleagues have reported that the new zfp91 gene for the first time was found in these patients with acute myeloid leukaemia and it expressed highly in most patients' leukaemia cells." (PMID 32677376, 2020). "Limited data concerning the function of ZFP91 product show that it is a potential transcription factor upregulated in human acute myelogenous leukemia and most recently found to be the non-canonical NF-κB pathway regulator." (PMID 24272675, 2014).
hepatocellular carcinoma (4 papers, 2019 to 2025). A malignant tumor that arises from hepatocytes. "Previous studies have found that ZFP91 (Zinc finger protein 91) can be a tumor suppressor for liver cancer occurrence and metabolic reprogramming, which can be a potential new prognostic biomarker and HCC (Hepatocellular Carcinoma) treatment target." (PMID 38110999, 2023).
cardiac hypertrophy (2 papers, 2020 to 2021). "Last, Adora1 agonist rescued heart dysfunction and cardiac hypertrophy in zfp91 loss mice after TAC." (PMID 32677376, 2020). "In the CC aspect, protein binding, channel activity and substrate‐specific channel activity may take an important role in the pathology of Zfp91 loss–induced cardiac hypertrophy (P < .01)." (PMID 32677376, 2020). "In the MF aspect, intracellular, cytoplasm and cell projection may play a great role in development of Zfp91 loss–induced cardiac hypertrophy (P < .01)." (PMID 32677376, 2020). "In the BP aspect, muscle system process, regulations of heart contraction and cardiac muscle contraction may be the key BPs involving in the development of Zfp91 loss–induced cardiac hypertrophy (P < .01)." (PMID 32677376, 2020). "Additionally, differentiated spliced TFs also function in cardiac fibrosis (e.g., KLF6), angiogenesis (e.g., VEZF1), cardiac structure and contractile function (e.g., VEZF1), cardiac hypertrophy, inflammation, and regulatory T-cell homeostasis (e.g., ZFP91)." (PMID 34977163, 2021).
leukaemia (2 papers, 2020 to 2022). "Then, we confirmed this result in 2 different ZFP91 knockdown leukemia cells, NB4 and KG1a." (PMID 35165513, 2022). "The expression level of RIP1 protein could be stabilized by MG132 in ZFP91 KD cells compared to the control cells, further indicating that the degradation of RIP1 in the leukemia cells depends on the proteasome pathway after the knockdown of ZFP91." (PMID 35165513, 2022). "First, we detected the mRNA expression levels of RIP1 after the knockdown of ZFP91 in NB4 and KG1a leukemia cells." (PMID 35165513, 2022).
multiple myeloma (2 papers, 2018 to 2022). "Ablation of UBE2G1 significantly diminished the degradation of IKFZ1, IKZF3 and ZFP91 by LEN, POM, and CC-220, as well as CK1α degradation by LEN in OPM2, DF15 and MM1S myeloma cells." (PMID 30234487, 2018).
T cell lymphoma (2 papers, 2024 to 2025). "To identify a tag that could efficiently knock down mouse PD-1, we connected various degron tags to the C-terminus of PD-1, including IKZF1/3, Sall4, ZFP91, and SD, and generated Jurkat human T cell lymphoma cell lines that stably expressed the mouse PD-1-degron tag." (PMID 40687785, 2025).
colorectal tumors (1 paper, 2014). "In a study of colorectal tumors, chromosomes 8 and 11 were involved in concurrent pulverization events with generation of fusion genes, involving e.g. SAPS3 and ZFP91." (PMID 24476156, 2014).
lung carcinoma (1 paper, 2025). "Furthermore, NIK activity is linked to the pathogenesis of lung cancer; therefore, ZFP91 may contribute to the development of this disease." (PMID 40860815, 2025). "Nevertheless, further studies are needed to elucidate the role of ZFP91 in lung cancer, particularly in NSCLC." (PMID 40860815, 2025). "Our study demonstrated that CuB suppressed ZFP91 and HIF-1α expression in A549 cells, though their functional interplay in lung cancer remains to be elucidated." (PMID 40860815, 2025). "However, it remains unclear whether ZFP91 is involved in the pathogenesis of lung cancer." (PMID 40860815, 2025).
Obesity (1 paper, 2024). Accumulation of substantial excess body fat. "The upregulated level of Zfp91 suggests the promising effect of Pineapple extract in managing obesity." (PMID 38931172, 2024).
psoriasis (1 paper, 2022). An autoimmune condition characterized by red, well-delineated plaques with silvery scales that are usually on the extensor surfaces and scalp. "Finally, we identified PUM1 and ZFP91 as the optimal diagnostic biomarkers for osteoarticular involvement in psoriasis and AS." (PMID 35371093, 2022). "Besides, our study revealed the mRNA surveillance pathway and two diagnostic gene biomarkers (PUM1 and ZFP91) for the osteoarticular involvement in psoriasis and AS." (PMID 35371093, 2022).
cancer (14 papers, 2014 to 2025). A tumor composed of atypical neoplastic, often pleomorphic cells that invade other tissues. "Herein, our data demonstrated that ZFP91 acts as a cancer promoter by inhibiting the K48-linked ubiquitination of RIP1, which promotes cell proliferation and suppresses cell apoptosis in AML." (PMID 35165513, 2022). "The patients with HCC and low ZFP91 levels had a higher risk of cancer recurrence and death compared with those classified as high ZFP91 levels." (PMID 32754263, 2020). "Previously, it has been reported that ZFP91 is an important oncoprotein that is associated with the proliferation and tumorigenesis of many human cancer cells." (PMID 27144516, 2016). "In other words, ZFP91 is a potential anti-cancer target, and is attracting attention as an application of PROTAC in drug target discovery." (PMID 40362266, 2025). "ZFP91 promotes cancer cell proliferation and carcinogenesis by activating the transcriptional coregulatory protein HIF-1 via NF-κB68." (PMID 37296281, 2023). "ZFP91 takes part in different biological processes, and it promotes cancer development by the control of the NF-кB signaling pathway, FOXA1, HIF-1α, and so on 29,31,44." (PMID 35165513, 2022). "A growing body of evidence has displayed that the dysregulation of ZFP91 is related to cancer growth 41-43." (PMID 35165513, 2022). "Given that ZFP91 has an essential effect on NF-κB pathway in other cancers 31,32, we investigated the potential role of ZFP91 in AML." (PMID 35165513, 2022). "ZFP91 suppresses cancer metabolism reprogramming and progression by ubiquitinating and degrading hnRNP A1 to regulate PKM splicing in HCC cells." (PMID 32754263, 2020). "The decrease of ZFP91 was positively associated with clinical stage (P = 0.010), TNM stage (P = 0.018) and recurrence of cancer (P = 0.023) in HCC." (PMID 32754263, 2020). "We found that ZFP91 suppresses cancer aerobic glycolysis in HCC cells by regulating the alternative splicing of glycolytic enzyme PKM pre-mRNA through hnRNP A1." (PMID 32754263, 2020). "In summary, we reveal a connection between ZFP91 and alternative splicing and cancer metabolism in HCC and find that ZFP91 is a potential tumor suppressor in HCC." (PMID 32754263, 2020). "We further investigated the effects of hnRNP F ubiquitination at Lys 185 on ZFP91-mediated cancer cell migration and invasion." (PMID 29706618, 2018). "On the other hand, the range of ZFP91 expression in cancer samples was very wide and specimens with similar expression as in control group were also present." (PMID 27975057, 2016). "In this regard, it would be of interest to study potential differences between patients with high ZFP91 expression in cancer samples and those with its expression unchanged." (PMID 27975057, 2016). "Long noncoding RNA (lncRNA) expressed by ZFP91 pseudogene would be therefore another one in an emerging group of pseudogene lncRNAs involved in cellular development and cancer pathogenesis." (PMID 27975057, 2016). "Western blotting analysis showed markedly higher protein levels of ZFP91 in all cancer cell lines in comparison with normal (PrEC) cells." (PMID 24272675, 2014). "ZFP91 has been reported to play a significant role in various cancers." (PMID 40860815, 2025). "Previous studies have demonstrated that ZFP91 plays a significant role in various cancer types." (PMID 40860815, 2025). "This indicated that ZFP91 might exert a significant effect on the development of AML as a cancer-promoting factor." (PMID 35165513, 2022). "ZFP91 seems to be an important molecule in many cancers including AML." (PMID 35165513, 2022). "This inspired us to envision the targeting of ZFP91 as an anti-cancer treatment strategy in AML, and the present research offers a theoretical foundation for this hypothesis." (PMID 35165513, 2022). "It has been reported that ZFP91 possesses cancer-promoting functions." (PMID 35165513, 2022).
cancer (continued). "Given that ZFP91 is a tumor promotor in several cancers, we wished to explore whether ZFP91 can affect AML cell propagation and cell cycle allocation." (PMID 35165513, 2022). "ZFP91, an E3 ligase, has been reported to possess cancer‐promoting functions." (PMID 33755268, 2021). "Therefore, our findings provide a novel regulatory of ZFP91 in cancer and enrich ZFP91 roles and mechanisms in cancer." (PMID 32754263, 2020). "By applying pSILAC to the potent anti-cancer therapeutic lenalidomide, we demonstrate that a single time point experiment could identify ZFP91 as novel lenalidomide-dependent CRL4CRBN substrate." (PMID 28530236, 2017). "With respect to previous reports, it is reasonable to suggest that ZFP91 could be associated with cancer at least through NIK activation, however, our study reveals previously unappreciated clinical significance and biological role of ZFP91 in cancer." (PMID 27144516, 2016). "ZFP91 relatively high abundance in cancer cells could result from its greater stability and accumulation in these cells." (PMID 24272675, 2014). "Collectively, our findings indicate that ECD promotes cancer invasion and metastasis by preventing E3 ligase ZFP91-mediated hnRNP F ubiquitination and degradation, suggesting that ECD may be a marker for poor prognosis and a potential therapeutic target for GC patients." (PMID 29706618, 2018). "ZFP91 may serve as a driver gene to activate HIF-1α transcription in the development of cancer." (PMID 27144516, 2016). "Given the ability of ZFP91, ZNF503, and ZC3H18 to interact with nucleic acids and their known links to cancer, we focused on the 3 ZFPs." (PMID 31841561, 2019). "After quantification of ZFP91 abundance in cells using GAPDH levels as a reference, markedly higher protein quantity was noted in all cancer cell lines comparing to normal prostate epithelial cells (PrEC)." (PMID 24272675, 2014). "Napabucasin is a STAT3 inhibitor that mainly acts on cancer stem cells, but a quantitative proteomics analysis of the napabucasin-based PROTAC molecule XD2-149 revealed that XD2-149 significantly reduces the level of ZFP91." (PMID 40362266, 2025). "To date, ZFP91 has been shown to be a key factor in activation of noncanonical NF-κB signaling pathway as well as to be involved in HIF-1α signaling in cancer cells." (PMID 27975057, 2016). "However, the functional roles of ZFP91 in cancer metabolism reprogramming have not been determined to date." (PMID 32754263, 2020). "Importantly, ZFP91 stabilizes and activates NIK, a crucial kinase for the non-canonical NF-κB pathway, which is associated with cancer growth and survival." (PMID 27144516, 2016). "In addition to the c-myc-induced transcription, we provide another fashion of the upregulation of hnRNP A1 protein levels in cancer cells in which the ubiquitin-mediated degradation of hnRNP A1 was impaired because the E3 ubiquitin ligase ZFP91 of hnRNP A1 was downregulated or absent in HCC cells." (PMID 32754263, 2020). "In vitro stimulation of cancer cells with TNF and LIGHT (peptide activating both canonical and alternative NF-κB signaling pathway) stimulates ZFP91 expression (in MCF-7 cells for TNF and HeLa cells for LIGHT) in a dose dependant manner." (PMID 27975057, 2016).
tumor (9 papers, 2016 to 2025). "Zinc finger protein 91 (ZFP91) is an innovative E3 ubiquitin ligase that has been linked to drug resistance in cancers and has been demonstrated to be increased in a range of tumor types." (PMID 38957318, 2024). "Grinding tumor tissues and conducting Western blot experiments demonstrated that CuB effectively reduced the protein expression levels of ZFP91, HIF-1α, c-Myc, Cyclin D1, VEGF, and MMP-9 in tumor tissues." (PMID 40860815, 2025). "Here, we proved that ZFP91 was negatively regulated by the tumor suppressor microRNA-129-5p in PC cells through dual-luciferase reporter gene experiment, PCR, and functional experiments." (PMID 34925523, 2021). "Then, we detected the protein level of ZFP91 in five human samples and ZFP91 expression was elevated in most tumour tissues compared with adjacent normal tissues." (PMID 33755268, 2021). "Breviscapine inhibited the proliferative and migrant ability of PC cells by upregulating the level of tumor suppressor microRNA-129-5p, thereby inhibiting the expression of its downstream target gene ZFP91." (PMID 34925523, 2021). "According to GEO data set, ZFP91 expression was also remarkably increased in tumour tissues compared with adjacent normal tissues." (PMID 33755268, 2021). "Collectively, our findings reveal that ZFP91 is a tumor suppressor in HCC, regulates the ubiquitination and degradation of a novel substrate, hnRNP A1, and suppresses HCC metabolism programming, cell proliferation and metastasis." (PMID 32754263, 2020). "Based on our findings in vitro, we performed tumor xenograft assays and found that the overexpression of ZFP91 enhanced the growth of HCT116 and KM12C cells in nude mouse." (PMID 27144516, 2016). "Taken together, LINC00491 could modulate the expression of miR-188-5p and ZFP91 to facilitate PC tumor growth." (PMID 35399733, 2022). "Similarly, the depressed expression of LINC00491 and the increase in miR-188-5p activity were detected, accompanied by decreased ZFP91 expression in tumor of sh-LINC00491 group compared with corresponding control." (PMID 35399733, 2022). "Therefore, the biological function roles of ZFP91 require assessment in each type of tumor in the future." (PMID 32754263, 2020). "Taken together, we conclude that ZFP91 promotes the tumor growth through HIF-1α in vivo." (PMID 27144516, 2016).
ZFP91 also shares sentences with these, for which no sentence is quoted: Benign Prostate Hyperplasia (2 papers); breast carcinoma (2); myelogenous leukemia (2); stomach cancer (2); acute lymphoblastic leukemia (1); glioma (1); hypertrophy (1); infection (1); lung adenocarcinoma (1); lymphoma (1); nasopharyngeal carcinoma (1); neuroblastoma (1); non-small cell lung carcinoma (1); pancreatic adenocarcinoma (1).